PIK3CA (phosphatidylinositol-4,5-bisphosphate 3-kinase catalytic subunit alpha)
Diseases named in the same sentence as PIK3CA in open-access papers (continued):
Sharing a sentence is not in itself a finding about the gene and the disease.
tumor (continued). "The PIK3CA gene also plays a crucial in tumor metastasis and tropism." (PMID 39369580, 2024). "In the present study, the tumor in case NCCLu-263 had a PIK3CA kinase domain (Y1021H) mutation and therefore did not respond to erlotinib." (PMID 38398169, 2024). "As the scientific narrative converges, this review underscores the critical role of PIK3CA in shaping the molecular intricacies of TNBC tumor tropism and illuminates pathways toward tailored interventions, promising a paradigm shift in the clinical management of TNBC." (PMID 39369580, 2024). "Further, significant differences were seen in the HER2 immunohistochemical status and HER2 status in the primary setting in patients with PIK3CA mutations in their relapse tumor as compared to those without mutations (p = 0.015 and p = 0.011, respectively)." (PMID 38822093, 2024). "In this study, the tumor process was stabilized without further metastasis due to a significant decrease in the NF-kB p65 subunit expression level thanks to PIK3CA inactivating mutations that downregulated the AKT expression level." (PMID 38392199, 2024). "By studying key gene mutations such as PIK3CA and FGFR1, more precise treatments could be developed to address these complex tumor traits." (PMID 39457636, 2024). "Further investigation of the ovarian histology was conducted, and the results were negative for the following tumor mutations: PIK3CA, KRAS, IDH1, and BRAF." (PMID 39816315, 2024). "For example, the PIK3CA inhibitor taselisib has been studied across 11 tumor types." (PMID 38938274, 2024). "Competitive behavior promoting tumor development has been well documented in the intestine, where oncogenic mutations in APC, KRAS, or PIK3CA facilitate tumorigenesis through both tumor cell-intrinsic effects on cell growth and non-cell-autonomous effects on neighboring cells." (PMID 37832945, 2024). "Co-mutation of PIK3CA and ARID1A enhances sustained IL-6 production, driving rapid tumor growth." (PMID 39445058, 2024). "For example, SNVs were identified in PIK3CA and KRAS across different cancer types and similarly pangenomic markers, such as homologous recombination deficiency (HRD) and tumor mutational burden (TMB), for which clinical trials may be available." (PMID 38200255, 2024). "Mutations in the PIK3CA gene can lead to sustained activation of the phosphatidylinositol 3-kinase (PI3K)/protein kinase B (AKT) signaling pathway, promoting the proliferation, survival, migration, invasion, angiogenesis, and drug resistance of tumor cells." (PMID 39555098, 2024). "We first assessed whether AKT (pAKT) activation was more frequently detected in tumours harbouring genetic alterations of the PIK3CA/AKT/mTOR axis compared to wild-type lesions using the IHC data." (PMID 39322687, 2024). "Although the mutational landscape in CRC is well known, differences in the frequency of mutations related to ethnicity have been reported; a higher frequency of mutations in PIK3CA, MAP2K1, and NF1 have been seen in tumor samples from patients of African American ethnicity compared to Caucasians." (PMID 38731914, 2024).
tumor (continued). "In this study, we transfected PIK3CA-overexpressing tumor cells (SiHa, C33A, and HeLa) with miR-29a, a microRNA extensively studied as a therapeutic candidate for oncogene suppression in various tumor types." (PMID 39590348, 2024). "This suggests that early detection of PIK3CA mutations is important and might help therapeutic decision making in those patients with a HER2-low tumor." (PMID 38279318, 2024). "Increased mutation of PIK3CA is evident in luminal A subtype, HER2- and ER-positive tumours." (PMID 38774756, 2024). "Furthermore, several HNSCCs carry cancer-associated mutations in the PIK3CA gene, which promotes signaling via the PI3K pathway and thus stimulates tumor cell growth." (PMID 39272833, 2024). "However, they found a higher frequency of PIK3CA alterations in T1 tumors, with a Ta:T1 ratio of 1:1, suggesting an important role in tumor aggressiveness." (PMID 39410541, 2024). "However, despite the comprehensive nature of WGS, only a fraction of cases harboured currently targetable genomic alterations, including small numbers of cases with tumour mutation burden (TMB) > 10 per MB and cases with KRAS and PIK3CA mutations." (PMID 37894318, 2023). "Collectively, our findings indicate that targeting mTOR rather than PI3K is more effective in reducing cell proliferation, tumor growth, cell migration, and stemness, independent of PIK3CA mutation status." (PMID 36792625, 2023). "If no mutation is found in ctDNA, testing in tumor tissue, if available, should be used as this will detect a small number of additional patients with PIK3CA mutations." (PMID 37760445, 2023). "Interestingly, PIK3CA mutations frequently co-occur with PTEN mutations or INPP4B overexpression, which accelerate tumor development." (PMID 37471270, 2023). "No PIK3CA mutations were observed in the remaining 28 tumor samples (62.2%) as well as blood samples." (PMID 37821962, 2023). "PIK3CA status was determined on both tumor tissue samples and plasma ctDNA." (PMID 36672617, 2023).
tumor (continued). "PIK3CA mutation activates the PI3K/AKT signaling pathway to promote tumor cell proliferation; DNA hypermethylation silences many tumor suppressor genes; overexpression of PD-L1 facilitates tumor cell immune escape and so on." (PMID 37784180, 2023). "Age distribution, histological SBR tumor grading, estrogen and progesterone receptors, human epidermal growth factor receptor 2, and molecular classification were not correlated with PIK3CA mutations (p > 0.05)." (PMID 37195967, 2023). "It appears that there is no direct relationship between PIK3CA mutations and tumor malignancy; however, we believe that further investigation is necessary through follow-up studies." (PMID 38033642, 2023). "PIK3CA gene status can vary among primary tumor and metastases." (PMID 36765661, 2023). "PIK3CA mutated and PIK3CA non-mutated cohort of patients were well balanced according to prognostic tumor characteristics." (PMID 37341201, 2023). "We chose this model due to observations that the PIK3CA mutation enhances COX-2 expression and promotes tumor proliferation via autocrine signaling, possibly informing eventual selection of patient populations that may be responsive to TPST-1495 therapy." (PMID 37559947, 2023). "Additionally, mutations in PIK3CA, FAM123B and KRAS were only associated with right-sided tumours (FDRmol < 0.05, hypergeometric test)." (PMID 37666855, 2023). "In patients with PIK3CA mutation each year of tamoxifen and AIs treatment decreased the risk of death by 32% and 27% in comparison to a patient with the same tumor characteristics who did not receive any ET, respectively." (PMID 37341201, 2023). "Therefore, we further explored PDX data to compare double mutant and single mutant PIK3CA tumors in terms of the tumor volume changes and drug responses." (PMID 36808143, 2023). "In particular, SLC31A2 and PIK3CA were copper homeostasis-regulated genes with a key role in tumor." (PMID 36973786, 2023). "Of note, we also showed that the discordance of PIK3CA mutational status was bi-directional, though more commonly observed from PIK3CA-mutated in primary tumor to wild-type status in the metastases rather than in the opposite direction." (PMID 37392328, 2023). "It indicates that the inhibition of PIK3CA and mTOR1 by the compounds achieved anti-tumor effects." (PMID 37834269, 2023). "Specifically, constitutively active NOTCH was shown to cooperate with different Pik3ca mutations (i.e., E545K and H1047R) during tumor initiation, but NOTCH also functioned as an allele-specific tumor suppressor in the presence of a transforming Pik3caH1047R allele." (PMID 38067308, 2023). "Among the 19 patients who developed benign tumours, only one (6%) carried somatic variant in KRAS, 16 (84%) showed a mutated HRAS allele, and two (10%) had mutations in PIK3CA genes; the 13 patients with cancer harboured somatic variants exclusively in the KRAS (31%) and HRAS (69%) genes." (PMID 37636262, 2023).
tumor (continued). "The mutation of PIK3CA, the encoding gene of PI3Kα, is one of the most common mutations in tumours and would result in the under-expression or absence of PTEN (phosphatase and tensin homolog) and hyperactivation of PI3K downstream signalling pathways." (PMID 37047827, 2023). "However, the consistency between plasma ctDNA and tumor tissue was poor in the SLOAR-1 trial, and only 177 of 317 patients with mutated PIK3CA were detected using plasma ctDNA." (PMID 38068930, 2023). "Tumor growth is extremely fast in double mutant PIK3CA compared to the single mutant." (PMID 36808143, 2023). "For instance, daily oral aspirin (≥75 mg/day) prevented distant tumor metastasis and reduced tumor morbidity and mortality and, furthermore, the survival of patients with CRC diagnosed with the PIK3CA variant can be prolonged by treating with routine oral aspirin (325 mg/day)." (PMID 37719444, 2023). "In conclusion, combination of low-dose metronomic VRL and alpelisib showed synergistic anti-tumor effects and significantly inhibited the growth of HR-positive, HER2-negative, PIK3CA-mutated BC cells, providing a rationale for further efforts to evaluate this combination in vivo." (PMID 36998707, 2023). "On the contrary, in the BELLE-2 trial, patients with PIK3CA mutations tested in tumor tissue, PFS was not different between treatments." (PMID 35565291, 2022). "Because in two cases a FGFR1 alteration in combination with PIK3CA or PIK3R1 mutation was present, the authors questioned whether such samples may represent a yet-to-be defined tumor class of RGNT outside of the stereotypic location in the fourth ventricle." (PMID 35018490, 2022). "The majority of samples for determination of PIK3CA/AKT1/PTEN status were from primary tumor tissue (143 [64%] primary, 66 [30%] metastatic, 10 [5%] unknown, three [1%] enrolled based on local testing with no central confirmation available)." (PMID 34860318, 2022). "They found that high expression levels of ERBB2 occurred in spheres showing hyperactive PI3K/AKT pathway and proved that triple targeting of ERBB2, MEK and PI3K induces CSC death and regression of anti-EGFR-resistant tumor xenografts, including those carrying KRAS and PIK3CA mutation." (PMID 35582524, 2022). "For example, FGFR3 was enriched greater than 8x in tumor-positive samples, while PIK3CA mutation and FGF3 amplification were never observed in post resection, negative surveillance cystoscopy samples." (PMID 36233691, 2022). "Mutations in the helical and kinase domain of PIK3CA have been previously associated with different outcome in patients with BC28 and double mutations were shown to induce increased PI3K activity and signaling and increased tumor proliferation." (PMID 35181669, 2022). "But knockout of p85β in RKO cells, which harbor a PIK3CA kinase domain mutation, had no impact on tumor growth." (PMID 35418124, 2022). "In contrast, lactate signaling in tumor cells increases glucose uptake, enhances expression and activity of glycolysis enzymes and reduces mitochondrial function via a mechanisms linked to HIF-1α and PIK3CA." (PMID 35693822, 2022). "The variant allele frequencies (VAFs) of the PIK3CA and NRAS mutations were relatively low (median, 6%; range, 1–38%), compatible with relatively low histopathologic estimated percentage of tumor nuclei (%TN) to overall cellular nuclei (median, 20%; range, 10–70%)." (PMID 35787784, 2022). "If PIK3CA mutation is not detected in plasma ctDNA specimen, it is recommended to harvest tumor tissue specimen to further clarify the PIK3CA mutation status." (PMID 38089455, 2022).
tumor (continued). "In node-negative, SHR-positive undifferentiated (G3) tumours, patients with a PIK3CA-mutation (n = 14) had a worse 5 year-RFI (70.5%) than those with wildtype PIK3CA (5 year RFI 96.4%, HR 11.92; 95% CI 1.724–82.461, p = 0.012)." (PMID 36279023, 2022). "Disease stabilization at 16 weeks was seen in six patients receiving the combination treatment (50%) and did not appear to correlate with the presence of PIK3CA mutation in archival tumor tissue." (PMID 36579519, 2022). "Another case that harbored missense mutations of the exonuclease domain of POLE (P286R and T323A), PIK3CA, ARID1A, and PTEN and a high tumor mutation burden (169 mutations per DNA megabase) achieved a durable response with pembrolizumab but was microsatellite stable." (PMID 36290878, 2022). "Mutation of PIK3CA can lead to enhanced kinase activity, which in turn continuously stimulates downstream AKT, increases cell invasion and metastasis, and promotes tumor development." (PMID 36568197, 2022). "Treatment of DMBA group with 7b and 14b resulted in significant reduction of PIK3CA expression which could be one of the factors that hinder tumor progression and facilitate its treatment." (PMID 35164019, 2022). "Then, we asked whether the detection of PIK3CA alterations would be identifiable in primary tumor samples and metastases using RT-PCR assays." (PMID 36428975, 2022). "Low-grade tumours ordinarily harbour relatively few genomic aberrations (often activating point mutations in oncogenes such as FGFR3, PIK3CA and RAS), typically exhibit luminal expression subtypes, and can be subdivided into two groups on the basis of CNVs (GS1 and GS2)." (PMID 35655252, 2022). "BC is further classified into several subclasses, characterized by immunohistochemical staining {(e.g., ER, PR, HER2 (ERBB2)}, proliferation marker protein Ki-67 (MKI67), genomic markers (e.g., BRCA1, BRCA2, and PIK3CA), and immunomarkers (e.g., tumor-infiltrating lymphocytes and PD-L1)." (PMID 36232989, 2022). "Additionally, genetic amplifications of the PIK3CA locus and mutations of the tumor suppressor Phosphatase and Tensin homolog (PTEN; 4%) drive tumor progression and therapy resistance 5,13,14." (PMID 35673573, 2022). "In addition, GDC-0077, compared with other PI3K inhibitors, shows stronger potency against PIK3CA-mutant cell lines in vitro and leads to greater tumor regression in PIK3CA-mutant xenograft models." (PMID 35806358, 2022). "Additional recurrent alterations in this tumor class comprised PIK3CA mutations (6/19; 32%), including classical hotspot mutations such as p.H1047 or p.E545, which are known predictive markers for treatment with PIK3 pathway inhibitors in breast cancer." (PMID 36443295, 2022). "To define the mutational status of PIK3CA using NGS and to assess whether this can be recapitulated by the primary tissue, we analyzed both the primary tumor samples when available (n = 8, 50.0%) and all the metastases (n = 16, 100%)." (PMID 36428975, 2022). "This patient with mutation of the PIK3CA gene was sensitive to platinum-based chemotherapy, showed a significant downwards trend in tumor markers, and did not have recurrence after a year of follow-up, indicating a reasonably good prognosis." (PMID 36123851, 2022).